FOXM1 (forkhead box M1)
Diseases named in the same sentence as FOXM1 in open-access papers (continued):
Sharing a sentence is not in itself a finding about the gene and the disease.
cancer (continued). "Recently, Forkhead box M1 (FOXM1), a member of the Forkhead box (FOX) transcription factor family, was recognized as a master regulator of progression in a variety of cancer cell types." (PMID 34740322, 2021). "Dacomitinib was also found to reduce FOXM1 activity in pancreatic ductal adenocarcinoma cancer (PDAC), which is another aggressive cancer with poor prognosis and high FOXM1 activity." (PMID 34205406, 2021). "FOXM1 and RHNO1 mRNA expression correlate in both normal tissues and cancer, including HGSC, and is one of the most highly correlated BDG pairs genome-wide in FTE and HGSC cell models." (PMID 33890574, 2021). "To explore the mechanism by which FoxM1 regulates STMN1 expression, we performed RT-qPCR to test the mRNA levels of STMN1 in FoxM1-knockdown cancer cell lines." (PMID 33526768, 2021). "Our results showed the inhibitory effect of avasimibe on CCA in vivo and in vitro and demonstrated that avasimibe targets FoxM1/AKR1C1 signaling, an essential pathway in tumorigenesis and cancer progression." (PMID 34127944, 2021). "To experimentally confirm FOXM1-suppressing effect of STL, we used human cancer cell lines of different origin." (PMID 34262016, 2021). "In this study, we investigated the anti-cancer effects of FDI-6, a FOXM1 inhibitor, as well as its molecular mechanisms, in TNBC cells." (PMID 34206484, 2021). "In these four cancer cells, FOXM1 expression is dependent upon DKK1-CKAP4 signaling, and FOXM1 transcription requires AKT and MEK activity." (PMID 34117362, 2021). "These 8 genes (SPP1, TTK, MELK, FOXM1, LYN, ARRB2, COL6A3, and CCL21) were further validated in more numbers of cancer tissue samples by quantitative real-time PCR (qRT-PCR)." (PMID 33829064, 2021). "In particular, FOXM1 regulation of cell cycle and mitotic genes, such as CCNB1, CDK1, and CENFP, is conserved across different cancer types." (PMID 34205406, 2021). "Enforced expression of GATA3 in HCT116 cells inhibited a series of cancer-promoting proteins, DNMT1, SETD1A, SETDB1, FOXM1, MYC, and MSI1." (PMID 34595169, 2021). "The interactive analysis tool was applied to confirm the expression level of the eight DEGs (SPP1, TTK, MELK, FOXM1, LYN, ARRB2, COL6A3, and CCL21) in cancer and normal tissues." (PMID 33829064, 2021). "Our study showed that FoxM1 upregulates STMN1 by transcriptional regulation, and the FoxM1-mediated transcriptional activation of STMN1 can promote cell proliferation and survival both in vitro and in vivo in LIHC, GC and CRC cancers." (PMID 33526768, 2021). "FGFR1 has been found to maintain the stem cell characteristics of cancer cells, through activation of MEK (mitogen-activated protein kinase kinase)/ERK pathways and forkhead box protein M1 (FOXM1) pathway." (PMID 33637089, 2021). "To investigate the functional relationship between FoxM1 and STMN1 in cancers, we used Western blot to observe the expression pattern of FoxM1 and STMN1 in 18 cancer cell lines derived from LIHC, GC and CRC." (PMID 33526768, 2021). "We observed that samples with high chromatin accessibility of CERES have high expression of CDKN1C, accompanied by low expression of genes involved in cancer cell proliferation (MKI67 and PCNA) and aggressiveness (FOXM1)." (PMID 34272384, 2021). "Meanwhile, the inhibition of FOXM1 repressed the expression of CDK6, CCND1, CDK2, CCNE2, E2F2, and CDC25A to arrest the cell cycle at G2 phase, which blocks the promotion of cancer-cell mitosis." (PMID 34880209, 2021). "ETC-168 can be used as a useful compound and surrogate tool to block oncogenic expression of E2F1, FOXM1, and WEE1 in human cancers." (PMID 33564073, 2021).
cancer (continued). "We asked next, how general is the correlation between FOXM1 expression and markers for replication stress (pS345 Chk1 and/or pS428 ATR) and FOXM1 transcriptional targets Cyclin B and RAD51 in cancer cell lines and tumor samples." (PMID 33253193, 2020). "Our data are consistent with published observations that FOXM1 and FOXO3A have opposite roles in cancer." (PMID 32967092, 2020). "Forkhead Box M1 (FOXM1) is an EMT-promoting factor in cancer, and its knockdown hampers the invasion and migration of cancer cells." (PMID 33066509, 2020). "Many APC substrates have been observed overexpressed in multiple cancer types, such as CDC20, the Aurora A and B kinases, and Forkhead box M1 (FOXM1), suggesting APC activity is important for cell health." (PMID 32805721, 2020). "In addition, because invasive properties of metastatic cancer cells are a necessary requirement for them to enter the bloodstream and facilitate transport to and lodging at distant organs, we also examined the effect of these FOXM1 inhibitory compounds on restricting cancer cell invasiveness." (PMID 32961773, 2020). "This suggests that although some cancer-specific enhancers are common to LUAD and BRCA, the enhancers regulated by CENPA, FOXM1, and MYBL2 are largely different between tumor types." (PMID 32925947, 2020). "AURKA has also been shown to negatively regulate FOXO1 at the transcriptional level, indicating that FOXM1 can indirectly regulate FOXO expression via AURKA to sustain its expression and activity in cancer cells." (PMID 32372224, 2020). "Expression of FOXM1 correlates directly with the expression of patched-1 (PTCH1), smoothened (SMO) and GLI1 in various cancers." (PMID 33680951, 2020). "Previous studies demonstrated that MELK interacts with and phosphorylates its downstream substrates including FOXM1, eukaryotic translation initiation factor 4B (eIF4B) and SQSTM1, and thus promotes the malignant phenotype of human cancer." (PMID 32047721, 2020). "Mechanistically, the activity of FoxM1 is regulated by MELK kinase in various cancer cells; however, the contribution of MELK-FoxM1 signaling in the process of DOC resistance acquisition in TNBC is never deeply investigated." (PMID 32581798, 2020). "Forkhead box M1 (FOXM1) is a downstream target of FOXO3a and is frequently upregulated in cancer cells." (PMID 31952105, 2020). "In total, 32 cancer related genes including CCND1, MKI67, HIF1A, CDH1, RRM2, and FOXM1 were subsequently identified through Ingenuity Pathway Analysis." (PMID 32348423, 2020). "Here we showed that CENPA, FOXM1, and MYBL2 are upregulated together, potentially leading to the activation of many cancer-specific enhancers in a subgroup of LUAD." (PMID 32925947, 2020). "When we compared our LUAD data with that of a similar analysis of BRCA, CENPA, FOXM1, and MYBL2 were also found to be activated, particularly in basal-subtype tumors, supporting the idea that these factors work together in certain cancer subtypes." (PMID 32925947, 2020). "We show that FOXM1 and PLAU are overexpressed in 17 cancer types including GC and the expression of these two genes are positively correlated with each other." (PMID 31949481, 2020). "It has also been observed that in some of the cancer cases even though GLI1 is altered at the initial stages, FOXM1 and GLI1 correlation is seen only when lymph node metastasis occurs." (PMID 33680951, 2020). "FOXM1 (also known as HFH-11B, Trident, Win and MPP2) is an oncogenic transcription factor which is known to be overexpressed during early cancer development." (PMID 32372224, 2020). "In our research, CKS2 interacts with maternal embryonic leucine zipper kinase and Forkhead Box M1 (FOXM1), which are closely related with malignant tumors, indicating that CKS2 plays an important role in lung ACA." (PMID 33083148, 2020).
cancer (continued). "While IHC has been successfully used to detect phospho-specific MYBL2 in human carcinomas, a more feasible approach would be to employ IHC panels detecting MYBL2 and MYBL2-regulated targets such as FOXM1, CHK1, and RAD51." (PMID 33489883, 2020). "As we know, FoxM1 has been widely reported to promote cell proliferation, invasion and EMT in multiple cancers." (PMID 31831728, 2019). "However, the mechanisms of action of FOXM1 in human cancers remain unclear." (PMID 31072351, 2019). "The overexpression of miR-149 increased the drug sensitivity of cancer cells and inhibited the EMT through the FOXM1/cyclin D1/MMP2 axis." (PMID 31552107, 2019). "Analyzing the interplay, we have zeroed in on E2F1, FOXM1 (transcription factors) and PVT1 (lncRNA) regulatory path as recurring pan-cancer regulatory entity." (PMID 30809433, 2019). "In summary, results here demonstrate that PLK1 and FOXM1 are participants in the hyperplastic phenotype of PAH HPASMC and support the cancer paradigm for PAH vascular cells proposed by Rai and coworkers." (PMID 31437238, 2019). "FOXM1 is a potent oncogene negatively regulated by FOXO3 and contributes to cancer drug resistance through controlling many genes involved in cell proliferation, survival, DNA repair, and tubulin destabilization." (PMID 31727006, 2019). "Our results indicated that RvD1 impaired paracrine of CAFs-derived COMP by targeting FPR2/ROS/FOXM1 signaling to repress EMT and cancer stemness in HCC." (PMID 30999932, 2019). "An in vitro systematic substrate screen in several cancer-derived cells lines concluded that CDK4/6 can phosphorylate and stabilize FOXM1 to promote entry into the S phase of the cell cycle." (PMID 30978209, 2019). "To further substantiate the clinical relevance of the B-Myb/FoxM1/Cdk/Plk1 axis we applied PRECOG, a pan-cancer resource of expression signatures that correlates cancer gene expression and clinical prognosis data through calculation of meta-z-scores." (PMID 30321399, 2019). "In this study, we mainly concentrated on the upstream mechanism by which RvD1 provided paracrine inhibition of CAFs-derived COMP via FPR2/ROS/FOXM1 cascades to prevent EMT and cancer stemness in HCC." (PMID 30999932, 2019). "Analysis from CHAT revealed that BIRC5, E2F2, KIF2C, FOXM1, and MCM5 were mainly involved in sustaining proliferative signaling in cancer development, with npmi values of 0.15, 0.222, 0.168, 0.218, and 0.157, respectively." (PMID 31579605, 2019). "From our network, we observed that E2F1 regulates POLD1, ASF1B, FOXM1 and RACGAP1 which are up-regulated in all 15 cancer types (Subnetwork)." (PMID 30809433, 2019). "It is worthwhile to note that only FOXM1, E2F1, and RAD51 showed positive correlations with UBE2C in all 27 cancers." (PMID 31067633, 2019). "We performed a comprehensive analysis of FOXM1 isoform expression in GTEx and TCGA normal, TCGA pan-cancer, and CCLE cell lines to determine the FOXM1 isoform expression profiles." (PMID 30795624, 2019). "FOXM1 and PLK1 are cooperatively overexpressed in various cancers and identified as potential therapeutic targets." (PMID 31185958, 2019). "As a transcription factor, FoxM1 has been reported to promote cell proliferation, migration, invasion and EMT in various cancers." (PMID 31831728, 2019). "FOXM1 is one of the YAP target genes, and is a driver of cell proliferation, chemo resistance and cancer progression." (PMID 30717152, 2019). "Our analyses revealed cancer types with distinct levels of FOXM1 copy number alterations and expression, including HGSC and BBC, which have highly elevated FOXM1, and THCA and PCPG, which show remarkably lower FOXM1." (PMID 30795624, 2019). "To understand how increased FOXM1 isoform expression in cancer relates to function, we used CRISPR to knock out FOXM1 in 293T cells." (PMID 30795624, 2019).
cancer (continued). "Combining RNA-RNA interaction prediction and transcription regulatory networks, we identified E2F1, FOXM1 and PVT1 regulatory path as recurring pan-cancer regulatory entity." (PMID 30809433, 2019). "FoxM1 has been shown in cancer cells to induce epithelial to mesenchymal transitions (EMT) and promotes cancer cell stemness." (PMID 31366108, 2019). "This study is to investigate the roles of FoxM1, by examining its regulation and the effect of FoxM1 overexpression or knockdown in NPC cells, and further detected in cancer biopsies." (PMID 30416986, 2018). "This is also confirmed in other cancer types where the ESC mRNA signature goes down upon chemical and pharmacological FOXM1 knock-down 37–39." (PMID 30504901, 2018). "Anticancer drugs that increase ROS production in cancer include bortezomib (Velcade), siomycin, thiostrepton and MG132, since these compounds inhibit the transcription activity of Forkhead Box M1 (FOXM1)." (PMID 29760743, 2018). "Furthermore, FoxM1-targeted therapy could effectively restrain tumor development of cancer." (PMID 29416660, 2018). "The FOXM1 network was shown to be the foremost predictor of adverse outcomes in a PRECOG dataset of 18,000 cancers." (PMID 30089730, 2018). "FOXM1 and UHRF1 were overexpressed in the taxane-resistant cancer cells, and positively regulated the maintenance of CSCs." (PMID 29752436, 2018). "We have previously published that CEP55 is a downstream target of FOXM1 oncogene and that CEP55 has been shown to be associated with ALIX and the ESCRT complex, we therefore asked if CEP55 protein may be enriched in cancer exosomes as it is known to be upregulated in cancer cells." (PMID 30008265, 2018). "Although every subfamily of FOX transcription factors exhibits biologically significant roles, FOXA, FOXM1, FOXO, FOXC and FOXP have received the most attention from the scientific community, especially in cancer research." (PMID 30360388, 2018). "Several transcription factors, such as oncoprotein FoxM1 and c-JUN, have been reported to promote MELK in cancer cells." (PMID 29416794, 2018). "Through targeting FoxM1 and Slug, overexpression of miR-630 is capable of suppressing EMT in various carcinomas." (PMID 29653565, 2018). "To investigate the impact of FOXM1 and Cath-D on cancer cell metastasis, we injected FOXM1-OE SGC7901, FOXM1-OE and Cath-D KD SGC7901 and their respective control into subcutaneous tissues of nude mice." (PMID 28978107, 2017). "We have previously published our bioinformatics meta-analysis on across over 40 different human cancer types available in Oncomine and NCBI's Gene Expression Omnibus (GEO) databases, showing that FOXM1 is one of the top oncogenes in HNSCC." (PMID 27409343, 2016). "Three genes (SOX4, FOXM1, and FOXQ1) were subsequently chosen for further investigation based on their known role in colorectal or other human cancer types." (PMID 27119506, 2016). "Previous studies have confirmed that FOXM1 was a downstream cellular target of EGFR signaling and had an important role in cancer development." (PMID 27494877, 2016). "Our data also suggest that FOXM1 and KIF20A can be useful predictive biomarkers, in addition to being therapeutic targets for cancer treatment and for tackling taxane resistance in cancer." (PMID 25961928, 2016). "Recently, the Forkhead transcription factor family, FOXQ1 and FOXM1 induce EMT and aggressiveness in human cancer." (PMID 27223064, 2016). "Other studies showed that FOXM1 and its downstream DNA damage repair targets BRCA1, BRCA2, and XRCC1 increased cisplatin resistance in different types of cancer cells, as well as herceptin and paclitaxel resistance in breast cancer cells." (PMID 25537512, 2015).
cancer (continued). "UHRF1 is known to regulate gene expression and the cell cycle and is overexpressed in many cancers, and it is of note that UHFR1 binds inverted CCAAT motifs perhaps enabling requirement of FOXM1 at these specific genomic binding sites." (PMID 26100407, 2015). "In the present study, we provided evidence that miR-34a, the novel prognostic marker in cancer, regulated senescence and viability in HCC tissues and cell lines, at least, by targeting the FoxM1 and c-Myc gene, in the telomere pathway." (PMID 25686834, 2015). "In cancer cells, MELK forms a protein complex with the transcription factor/oncogene FOXM1, a master regulator for cell cycle progression." (PMID 25852826, 2015). "Consequently it has been argued that targeting FOXM1 could provide an opportunity to treat cancer." (PMID 26258070, 2015). "These merged DMxDE datasets suggest some known or previously reported/suspected cancer genes [PR: SPARCL1, NQO1, CST1, MELK1, DPT, FAM83A, MMP9; GB: FOXM1, TFAP2, GREM1, ITGA8, GRIA1, SLIT3] as well as many previously unreported genes/loci." (PMID 26683690, 2015). "Together our data demonstrate that there are global changes to the FOXM1 regulatory network in OAC and the expression of components of this network help predict cancer prognosis." (PMID 25889361, 2015). "We propose that inhibiting the interactions between FOXM1 and NPM by chemical compounds or small specific peptides will suppress FOXM1 expression in cancer cells." (PMID 25093142, 2014). "This review will discuss the emerging insights into the role of FOXM1 in the DDR, in particular evaluating its implications on cancer initiation and genotoxic agent resistance." (PMID 25287128, 2014). "FOXM1 (FC = 1, FDR = 6.7e-06) and CDCA3 (FC = 1.2, FDR = 6.3e-07) are two representative genes overexpressed in late stage cancer, which also had high correlation coefficients between CNV and expression level (R = 0.70 and R = 0.54, respectively)." (PMID 25648588, 2014). "Previous research has demonstrated that up-regulation of FOXM1 increased the expression of MMP-2, MMP-9 and VEGF-A, resulting in the promotion of proliferation, migration and invasion of cancer cells." (PMID 24885308, 2014). "We concentrated in particular on studying the role of FOXM1 in regulating the expression of ABCG2 because ABCG2, also known as breast cancer resistance protein, belongs to the ATP-binding cassette family." (PMID 25213081, 2014). "Besides FoxM1, the oncogene myc is also negatively regulated by FoxO3a, and this regulation may have a key function in the control of cellular metabolism during cancer initiation and progression." (PMID 25401090, 2014). "The Forkhead box M1 (FOXM1), an important regulator of cell differentiation and proliferation, is overexpressed in a number of aggressive human carcinomas." (PMID 24885308, 2014). "Heterogeneity of Forkhead box M1 (FOXM1), matrix metallopeptidase 9 (MMP9), and pituitary tumor-transforming 1 (PTTG1) were involved in cancer invasion and migration." (PMID 23577100, 2013). "The 2Chr7:1n,1d cells exhibited a more invasive phenotype by expressing higher levels of the pro-invasive genes (IGFBP2, PDGFRA, RHOC, FOXM1, and PLAU) and matrix metalloproteinase 2 (MMP2), all of which are well-reported for cancers, including GBM." (PMID 24282558, 2013). "Prior studies have suggested that both FOXM1 and MELK play essential roles in cell cycle progression, cancer cell growth, and maintenance of stem cell state of GBM." (PMID 23404835, 2013). "Prior studies have suggested that both FOXM1 and MELK play essential roles in the cell cycle progression, cancer cell growth, and maintenance of stem cell state of GBM." (PMID 23404835, 2013).